EGFR (epidermal growth factor receptor)
Diseases named in the same sentence as EGFR in open-access papers (continued):
Sharing a sentence is not in itself a finding about the gene and the disease.
cancer (continued). "Although EGFR was beneficial to the barrier defense against infection, repeated activation of growth-promoting signals such as EGFR-linked pathways after toxic or inflammatory insults would ultimately contribute to cancer cell survival and tumorigenesis progression." (PMID 32461676, 2020). "On the basis of these findings and previous observations showing that AHR plays a role in cancer cell proliferation by interacting with growth factor receptors including EGFR, we explored whether a physical association of GPER with AHR and EGFR may occur in SkBr3 cells upon exposure to 3MC." (PMID 31370872, 2019). "Hence, compounds VM25 or VM26 could induce the degradation of EGFR and associated nutrient-prone proteins in cancer cells during growth in the serum-deprived medium." (PMID 31374910, 2019). "Previous reports suggested that dysregulation of signaling receptors including EGFR is frequently associated with cancer, since it may continue to its signaling activity from endocytic compartments and it also leads to the increased and uncontrolled receptor signaling." (PMID 35582586, 2019). "If the EGFR could be implicated in laminitis pathophysiology an array of new therapeutic options for treating the disease (i.e. EGFR antagonists) could be readily adapted from cancer therapeutics for laminitis treatment." (PMID 31805097, 2019). "Moreover, downregulation of EGFR protein causes cancer cell death through induction of mitophagy." (PMID 31121829, 2019). "Furthermore, both Hif-1α and Hif-2α are frequently overexpressed in NSCLC correlating, in some cases, with poor prognosis and Hif-1α expression is associated with resistance to cancer therapy, including EGFR (epidermal growth factor receptor 1) inhibitors in NSCLC." (PMID 31795465, 2019). "Heregulin might cause resistance to EGFR-targeted therapy in numerous types of cancer." (PMID 31570699, 2019). "AC could be described as a “gain-of-function” cancer, as most AC patients carry “gain-of-function” mutations or structural alterations in oncogenes involving the receptor tyrosine kinase pathway, such as L858R mutations in EGFR and ALK-EML4 fusion genes." (PMID 31069257, 2019). "Therefore, given the lack of effective therapeutic strategies against KRAS-mutated cancers, it might be of interest to test the capacity of afatinib alone or combined with other drugs to inhibit the growth of EGFR/KRAS co-mutated NSCLC in human patients." (PMID 31266248, 2019). "In several studies, sidedness was found not only to be prognostic in favor of left-sided cancer but also predictive of treatment outcome, with improved survival associated with use of combination chemotherapy plus epidermal growth factor receptor (EGFR) targeted antibodies." (PMID 31188892, 2019). "Other genes involved in HPV− HNSCC include the epidermal growth factor receptor (EGFR), often amplified in HNSCCs and related to cell cycle control, and Met, a receptor tyrosine kinase often associated with enhanced migration, invasion, and angiogenesis when overexpressed in cancer." (PMID 31861809, 2019). "Interestingly, NRF2 mutation occurs often in NSCLC but appears very rare in EGFR mutant cancer." (PMID 31221965, 2019). "To evaluate whether EGF-induced EGFR-c-Src activation is critical for the phosphorylation of Y328 and Y331 on HDAC3 and determine its association with the malignant behavior of cancer cells, we transiently transfected EGFR in MCF7 cells, which express low levels of EGFR." (PMID 31430896, 2019). "However, EGFR-TKI resistance or T790M mutation in carcinoma cells itself could induce p22phox and the status of p22phox in LUAD tissues without T790M mutation was by no means correlated with any of the clinicopathological factors examined." (PMID 30800222, 2019). "However, cancer cells with EGFR T790M and ALK L1196M mutations acquire drug resistance." (PMID 29721209, 2018).
cancer (continued). "Likewise, hRNase5/ANG secreted from cancer cells may associate with EGFR on the endothelial cell to play a role in angiogenesis." (PMID 30449278, 2018). "It has been thought that a small number of cancer cells having a secondary T790M mutation in addition to the active EGFR mutation may already be present prior to treatment with EGFR-TKIs and gradually become dominant during treatment with first-generation EGFR-TKIs (e.g., gefitinib and erlotinib)." (PMID 30445769, 2018). "Thus, we examined the frequency of an extended panel of cancer-relevant mutations that could potentially reduce the initial response to TKIs in a cohort of newly diagnosed, EGFR-mutated, advanced NSCLC of primarily ADC subtype." (PMID 29899852, 2018). "However, radiation upregulates cancer-promoting genes, such as EGFR, thereby causing resistance." (PMID 30111747, 2018). "Importantly, the occurrence of co-mutations in EGFR itself or other cancer-drivers at diagnosis may potentially impair the efficacy of tyrosine-kinase-inhibitors (TKIs) and partly explain why approximately 10% of TKI-treated NSCLCs are intrinsically resistant." (PMID 29899852, 2018). ": a coding sequence variant in the cancer gene, a total copy number = 0 (homozygous deletion) or ≥ 8 (amplification), we grouped the unassayed cell lines based on their EGFR mutation profiles and found that the EGFR mutated cell lines were significantly more sensitive to lapatinib." (PMID 30321817, 2018). "However, the results of randomized phase II study in NSCLC cancer patients selected for the presence of activating EGFR gene mutations demonstrated a clinically relevant increase of PFS by the combined treatment with erlotinib associated with bevacizumab compared erlotinib alone." (PMID 29270405, 2017). "Moreover, EGFR-induced DNA breakdown at specific sequence positions has been observed to up-regulate gene expression and even induce further gene mutation accumulation and subsequent cancer development." (PMID 28272528, 2017). "Indeed, correlation of E-cadherin protein expression in CRC, NSCLC and urothelial cancer cells with response to EGFR-targeted therapy showed that E-cadherin “loss” (with possible induction of soluble E-cadherin) points towards EGFR-targeted treatment resistance." (PMID 28199979, 2017). "Also mutations in the ectodomain of the EGFR can have a strong impact on cancer progression." (PMID 28417948, 2017). "Moreover, carcinomas with EGFR overexpression were associated with poor prognosis." (PMID 28157706, 2017). "The fourth case (P0015) is cancer of unknown origin with a rare activating EGFR mutation p.D587H." (PMID 27245685, 2016). "Also, mutations in exon 20 of the PIK3CA gene may be associated with anti-EGFR resistance in KRAS wild-type cancer." (PMID 27699178, 2016). "Taken together with the EGFR‐driven/mesenchymal classification of the case, we speculated that the loss of the miR‐15a/16 cluster enhances growth factor‐stimulated cell invasion here, as has been described in other cancers." (PMID 27888226, 2016). "If loss of PTEN is frequent among EGFR-positive cancer, then this may be a contributing factor to the significant resistance to EGFR inhibitors seen in the clinic and further stresses the potential importance of combination therapies against both EGFR/MAPK and PTEN/PI3K/AKT signaling pathways." (PMID 27484095, 2016). "Thus, targeting EGFR with photoactive molecules linked to anti-EGFR antibodies may selectively destroy cancer cells whilst sparing adjacent normal cells expressing low levels of EGFR." (PMID 27598202, 2016). "An analysis of the evolutionary dynamics of cancer cells with KRAS mutations in patients with colorectal cancer after treatment demonstrated that these mutations had been present before the initiation of EGFR blockade, in rare subclones harboring approximately thousands of cancer cells." (PMID 26912072, 2016).
cancer (continued). "However, when ATII cells acquired a K-RAS mutation and/or EGFR mutation, they could be transformed into cancer cells." (PMID 26167183, 2015). "These include recognised tests such as RAS, BRAF and EGFR mutation detection, OncotypeDX, Mammaprint and a range of emerging next generation sequencing oncology panels which will further enhance the molecular profiling of tumors and the targeted treatment of cancer patients." (PMID 26317646, 2015). "In addition, anti-EGFR/HGNs manipulate the cancer cell cycle to enhance radiation susceptibility." (PMID 25995714, 2015). "Therefore, inhibition of EGFR and c-Met and their associated signaling pathways could be a potent strategy for cancer therapy." (PMID 25405368, 2015). "Certain cancers associated with activating mutations of EGFR also appear to influence phosphorylation and expression of members of DDR response pathways, including phospho-DNAPK, ATM, and RAD51 foci, suggesting that both HRR and NHEJ pathways may have roles in conferring radioresistance." (PMID 26546517, 2015). "This suggests that EGFR may serve as a biological marker to identify high-risk subgroups and guide prophylactic therapy with chemopreventive drugs or surgical intervention to prevent progression to carcinoma." (PMID 26697149, 2015). "Moreover, miR-21 is positively regulated by EGFR signaling in cancer cells harboring activating EGFR mutations, and EGFR-TKIs can repress the aberrantly increased miR-21 levels, while miR-21 suppression could enhance EGFR TKIs therapeutic effects." (PMID 25593996, 2014). "Thus, KRAS and EGFR might have a role as markers of lung function impairment that may reflect cancer risk." (PMID 23384026, 2013). "Therefore, blocking of IL-6 signaling could be beneficial to cancer patients undergoing EGFR-TKI treatment for reducing the risk of its unfavorable effects." (PMID 23592411, 2013). "Genetic variants near TERT are strongly associated with predisposition to eight or more different cancer types, suggesting a potential mechanism by which rs7736074 and rs4975596 could influence the oncogenic potential of the EGFR signaling pathway through modulation of TERT activity." (PMID 24152305, 2013). "In addition, some forms of cancer are associated with increased levels of circulating EGFR ECD." (PMID 23990977, 2013). "Therefore, EGFR is a potential cancer therapy target and methods of inhibiting EGFR activity and associated signal transduction have been intensively studied, including specific antibodies against EGFR and inhibitors of EGFR." (PMID 24273605, 2013). "Mutations affecting EGFR expression or activity could result in cancer." (PMID 22619725, 2012). "Furthermore, this frequency for the loss of the mutant EGFR in recurrent NSCLC patients might be overestimated because the number of cancer cells in pleural and cerebrospinal fluids tested by cytological analysis was limited." (PMID 22815900, 2012). "In addition, mPRα expression may also associate with EGFR + cancers and cancers with higher level of Ki67 expression." (PMID 22496908, 2012). "Aberrant signaling can be the result of EGFR overexpression by EGFR gene amplification or mutations with ligand-independent tyrosine kinase activity which could result in uncontrolled cell division; a predisposition for cancer." (PMID 22300665, 2012). "Increased Met signaling in human cancers can be the result of enhanced ligand-binding (autocrine and paracrine), Met overexpression or missense mutations that often induce constitutive kinase activity, failure of Met down regulation and interactions with other cell surface receptors such as EGFR." (PMID 21776391, 2011). "In this hypothetical scheme, an overly active SCD1 could contribute to the overactivation of mitogenic signaling cascades associated to epidermal growth factor receptor (EGFR), insulin and insulin-like growth factor receptors, typically observed in a number of cancers." (PMID 24212819, 2011).
cancer (continued). "More studies are needed in large cohorts of cancer patients with familiar history of cancer in order to link EGFR germ-line mutations to development of the disease, but these results and precedent observations do suggest that EGFR is a candidate to be involved in familial oncogenesis." (PMID 21575252, 2011). "In addition to being overexpressed, EGFR is also found to be mutated in different cancers." (PMID 20828404, 2010). "Therefore, our model suggests that a drug capable of increasing the rate of EGFR degradation or capable of somehow tagging mutated EGFRs for degradation could be a useful developments in cancer treatment." (PMID 19804630, 2009). "As mutational activation of EGFR imparts a higher sensitivity to inhibition by EGFR-selective tyrosine kinase inhibitors (TKIs), there is considerable interest in understanding biological mechanisms whereby mutant EGFRs mediate aberrant oncogenic signaling in cancer cells." (PMID 19948031, 2009). "However, studies of the association between EGFR and cancer development in OS patients are few." (PMID 19662227, 2007). "Finally, the EGFR gene mutation may be lost in some cancer cells with other additional mechanisms of activating Akt." (PMID 15870831, 2005). "ERRFI1, encoding the epidermal growth factor receptor (EGFR) inhibitor MIG6, is mutated in various cancers, including BTC, representing a potential predictive biomarker." (PMID 42234947, 2026). "Drugs bound to albumin selectively target cancer cells with upregulated macropinocytosis, a process driven by constitutively hyper‐activated EGFR/RAS/PIK3CA signaling, which is common in HNSCC." (PMID 41521502, 2026). "Caveolin-1 (Cav-1) promotes anoikis resistance in cancer cells by stabilizing anti-apoptotic proteins like Mcl-1 and activating survival pathways such as Src/EGFR/ITGB1, PI3K/Akt, and MEK/ERK, facilitating anchorage-independent growth and metastasis." (PMID 41596231, 2026). "Building on the success of HPV and HBV vaccines, researchers are now developing innovative vaccine approaches targeting oncogenic drivers like KRAS, EGFR, and other early oncogenic neoantigens to intercept cancer before it emerges." (PMID 42001483, 2026). "Strikingly, the active conformation of EGFR and high levels of ATP binding were maintained regardless of ligand binding with high anionic lipid content typical of cancer cells, where EGFR signaling is enhanced." (PMID 41979597, 2026). "Collectively, these results establish that LAPTM4B promotes EGFR-TKI resistance by maintaining lysosomal acidification, thereby sustaining p-EGFR signaling and supporting cancer cell survival under TKI treatment." (PMID 41362742, 2026). "In AR-overexpressing NPC-B13 cells, AR appeared to regulate thyroid transcription factor-1 (TTF-1, encoded by NKX2-1 gene) and its downstream target epidermal growth factor receptor (EGFR), thereby promoting cancer cell proliferation." (PMID 41633021, 2026). "Drugs bound to albumin selectively target cancer cells with upregulated macropinocytosis, an endocytic nutrient‐scavenging process driven by constitutive hyper‐activation of the EGFR/RAS/PIK3CA signaling and Syndecan1 pathways." (PMID 41521502, 2026). "In this study, we confirmed that MSLN, an elevated protein in liver preferential metastasis-derived cells, interacts with EGFR to activate downstream signaling pathways, thereby promoting cancer metastasis." (PMID 41513618, 2026). "Potential roles of targets including Akt1, PPARG, and EGFR, as well as pathways related to cancer and lipid metabolism, were further indicated by network pharmacology and molecular docking." (PMID 42198446, 2026). "Mechanistically, both low-dose EGFR degraders and inhibitors elevate ROS levels and induce lipid peroxidation, thereby sensitizing cancer cells to GEM/DAC-triggered ferroptosis." (PMID 42190815, 2026). "Functional studies unveiled that EGFR activation suppressed the cellular response to IFN-γ following ICB treatment across multiple cancer models." (PMID 41538362, 2026).
cancer (continued). "Fusion peptides significantly induced apoptosis and reduced survival in EGFR/MMP-2 high cancer cells, while sparing EGFR/MMP-2 low cells in standard tissue culture and 3D-spheroids." (PMID 41920242, 2026). "Our results suggest that the global levels of EGFR packaged into EVs parallels its expression in parental cancer cells." (PMID 41953752, 2026). "Among the most prevalent mutations in NSCLC, epidermal growth factor receptor 1 (EGFR) and Kirsten rat sarcoma (KRAS) alterations play a key role in cancer progression and patient survival." (PMID 41995791, 2026). "The epidermal growth factor receptor (EGFR) is one of the most extensively studied targets in cancer therapy, yet its complex regulatory mechanisms remain partially understood." (PMID 42249090, 2026). "In vitro, Type-I UPTAB achieved near-complete degradation of EGFR and PD-L1 across multiple cancer cell lines, with optimal linker length critical for maximal activity." (PMID 42138807, 2026). "RESULTS: We identified the DNA base lesion repair proteins OGG1 and APE1 as key mediators of transcriptional reprogramming that promote cancer cell plasticity and resistance to EGFR-TKIs." (PMID 41975505, 2026). "We conclude that EGFR-MMP-MP1 peptides represent a novel cancer therapeutic for further development." (PMID 41920242, 2026). "The effects of the derivatives on various cancer cell lines in terms of cytotoxic/cytostatic activity, interference with cell cycle phase distribution, and suppression of EGFR phosphorylation set the basis for the design of more potent derivatives." (PMID 41751873, 2026). "The continuous adaptation of cancer cells to EGFR-targeted therapies represents a significant challenge in maintaining long-term treatment efficacy." (PMID 41522352, 2026). "Unlike many cancer vaccines designed to elicit potent CTL responses, CIMAvax-EGF intends to starve cancer cells overexpressing epidermal growth factor receptor (EGFR) through the generation of neutralizing antibodies against its cognate ligand, EGF." (PMID 41542091, 2025). "The measurement of cellular electrical properties has emerged as a promising method for cancer diagnostics, particularly through the analysis of epidermal growth factor receptor (EGFR) expression, which is frequently overexpressed in various malignancies." (PMID 41294763, 2025). "Among RTK family, the epidermal growth factor receptor (EGFR) is particularly well-studied in cancer." (PMID 40783393, 2025). "Epidermal growth factor receptor/mitogen-activated protein kinase (EGFR/MAPK) signaling is highly activated in various types of cancer." (PMID 40190348, 2025). "miR-126 targets genes that are implicated in key signaling pathways linked to the development of cancer, including the EGFR (epidermal growth factor receptor) and VEGFR (vascular endothelial growth factor receptor) pathways." (PMID 40227645, 2025). "Therapeutically, targeting this axis improves EGFR tyrosine kinase inhibitor (TKI) sensitivity: DHHC20 inhibition increases cancer cell dependence on EGFR signaling, sensitizing tumors to TKIs." (PMID 40977744, 2025). "For instance, following EGFR signaling inhibition, cancer cells often increase the expression and activation of alternative receptors such as MET or IGF-1R, thus activating bypass survival pathways and acquiring therapeutic resistance." (PMID 40872476, 2025). "The crosstalk between hypoxia and EGFR signaling has attracted increasing attention in cancer research." (PMID 40940319, 2025). "The peptide Herdegradin, which downregulates EGFR, stimulates mitophagy through the mTORC2/Akt pathway, effectively inhibiting the growth of EGFR-positive cancers, such as PCa, ultimately inducing the death of PCa cells." (PMID 40078274, 2025). "In conclusion, nanocarriers modified with anti-EGFR targeting ligands represent a promising approach for targeted cancer therapy, offering enhanced specificity and efficacy for cancer treatment." (PMID 39940134, 2025).